NNMT (nicotinamide N-methyltransferase)
Diseases named in the same sentence as NNMT in open-access papers (continued):
Sharing a sentence is not in itself a finding about the gene and the disease.
ovarian carcinoma (continued). "High level of STAT3 expression and its activity was recorded in metabolically plastic, glucose deprivation-resistant, ovarian cancer cells, accompanied by increased expression of metabolic genes G6PD, GLUT1 (Glucose transporter 1) and NNMT (nicotinamide N-methyltransferase)." (PMID 30857125, 2019). "Since NNMT expression is absent in both OVCAR3 and OAW28 epithelial ovarian cancer cell lines but highly induced in glucose-restricted sublines, we next sought to determine the upstream mechanisms controlling NNMT expression." (PMID 28412735, 2017). "For instance, systematic comparisons between HCC and NNMT-high malignancies (e.g., breast and ovarian cancers) could delineate conserved pathways (e.g., NAD+ salvage mechanisms) versus liver-specific vulnerabilities, such as the GNMT–NNMT regulatory axis in methionine cycle homeostasis." (PMID 40427612, 2025). "Interestingly, by knocking down NNMT in PRDX6‐WT‐overexpressing cells, we found that NNMT KD markedly abolished the promoting effect of PRDX6‐WT on the growth and proliferation of ovarian cancer cells, as evidenced by cell viability and colony formation assays." (PMID 39887931, 2025). "To investigate the effect of the PRDX6‐NNMT axis on the growth of ovarian cancer cells in vivo, we generated a mouse xenograft model by subcutaneously inoculating PRDX6‐overexpressing SKOV3 cells with or without NNMT KD into immunodeficient mice." (PMID 39887931, 2025). "We validated these results by overexpressing ZEB1 in another ovarian cancer cell line of serous histology (OVCA433), which shows no detectable endogenous expression of NNMT or ZEB1." (PMID 28412735, 2017). "In conclusion, our results demonstrated that beyond its canonical enzyme activities, PRDX6 promotes the malignant progression of ovarian cancer through a nonenzymatic mechanism, by which PRDX6 interacts with NNMT and suppresses TRIM56‐mediated ubiquitination degradation of NNMT." (PMID 39887931, 2025). "Given that PRDX6 upregulates NNMT independently of its enzymatic activities, we next investigated whether NNMT upregulation contributes to PRDX6's nonenzymatic function in promoting ovarian cancer progression." (PMID 39887931, 2025).
gastric cancer (25 papers, 2009 to 2025). A primary or metastatic malignant neoplasm involving the stomach. "In the gastric cancer microenvironment, cancer-associated fibroblasts upregulate Nicotinamide N-methyltransferase (NNMT) through FTO-mediated m6A demethylation, inducing M2 polarization and suppressing CD8+ T cell function." (PMID 41459510, 2025). "Analyses performed in MKN28, SGC7901, MGC803, and BGC823 gastric cancer cell lines revealed that NNMT knockdown was significantly associated with the inhibition of cell proliferation, invasion, and migration in vitro, as well as tumor formation in vivo." (PMID 36139012, 2022). "For example, increased expression of NNMT was associated with a worse prognosis in gastric cancer and pancreatic cancer." (PMID 33446144, 2021). "In our study, we investigated the association between NNMT expression levels and prognosis for solid tumors (glioblastoma, gastric cancer, pancreatic cancer, prostate cancer, nasopharyngeal cancer, lung cancer, hepatocellular cancer, and renal cancer)." (PMID 30349486, 2018). "The association of metastatic NNMT overexpression with lower DSS is in keeping with results from earlier studies reporting NNMT overexpression in the primary tumor to be a poor prognostic factor in gastric cancer, pancreatic cancer, and hepatocellular carcinoma." (PMID 31652035, 2019). "Although the inhibition of NNMT proteasomal degradation has been reported in gastric cancer, we here further characterized TRIM56 as the key E3 ubiquitin ligase for NNMT ubiquitination, and identified lysine 23 and 210 as its major ubiquitination sites." (PMID 39887931, 2025). "NNMT is known to promote epithelial-mesenchymal transition in gastric cancer cells and is probably involved in similar processes in the tadpole blastema." (PMID 36927452, 2023). "NNMT promotes epithelial-mesenchymal transition (EMT) in gastric cancer cells by activating transforming growth factor-β1 expression." (PMID 36817086, 2023). "NNMT is overexpressed in a variety of tumors and has been shown to promote progression and poor prognosis of several malignant tumors, such as gastric cancer, esophageal cancer and colorectal cancer." (PMID 36291696, 2022). "Previous studies have showed that NNMT expression had the potential capacity to predict the prognosis of several cancers, such as endometrial cancer, pancreatic cancer, and gastric cancer." (PMID 35233465, 2022). "As a small molecule methyltransferase in the human body responsible for the N-methylation of the nicotinamide, NNMT has been reported to promote proliferation or migration of several malignant tumors, including gastric cancer, esophageal cancer and OSCC." (PMID 36291696, 2022). "Correlation of NNMT expression and prognosis in gastric cancer with various clinicopathological factors." (PMID 33193702, 2020). "Growing evidence shows that NNMT is aberrantly expressed in several cancers and is a promising prognostic predictor in some of cancers, such as pancreatic cancer and gastric carcinoma." (PMID 31101119, 2019). "In tumors, abnormal expression of NNMT has been reported in glioblastoma, stomach cancer, papillary thyroid cancer, colon cancer, and renal carcinoma." (PMID 19216803, 2009). "Despite OAC’s genetic differences to OSCC and gastric cancer, there is mounting evidence that increased nicotinamide N-methyltransferase (NNMT) enzyme expression may play a pivotal role in cancer growth, metastasis and chemoresistance." (PMID 35205743, 2022). "In addition, silencing NNMT in gastric cancer cells significantly increased the proportion of cells in the G2 phase and inhibited cell activity." (PMID 36386816, 2022). "In addition, nicotinamide N-methyltransferase (NNMT) was found to be overexpressed in gastric carcinoma tissue compared with adjacent tissues and is related to poor prognosis." (PMID 33986766, 2021).
gastric cancer (continued). "Moreover, NNMT dysregulation has been shown to be a contributing factor to the progression of gastric cancer, pancreatic cancer, prostate cancer, nasopharyngeal cancer, lung cancer, hepatocellular cancer, and renal cancer." (PMID 30349486, 2018). "Interestingly, high NNMT expression levels correlate with poor prognosis in patients with glioblastoma, gastric cancer, and pancreatic cancer." (PMID 30349486, 2018). "These are the only two reports that we could find in the literature regarding the involvement of NNMT in gastric cancer." (PMID 27941907, 2016). "According to previous studies, NNMT was abundant in the cytoplasm and overexpressed in a variety of human malignant tumors, including lung cancer, glioblastoma, gastric cancer, pancreatic cancer, and colorectal cancer, suggesting that NNMT may be a co-carcinogenic factor in malignancies." (PMID 36386816, 2022). "Overexpression of TTPAL in gastric cancer cells upregulated NNMT, indicating that TTPAL stabilized NNMT in the PI3K/AKT signaling pathway." (PMID 35338115, 2022). "Co-IP and confocal immunofluorescence experiments showed that NNMT interacted and co-localized with alpha-tocopherol transfer protein-like (TTPAL), which was upregulated and correlated with poor survival in gastric cancer." (PMID 35338115, 2022). "NNMT expression was related with MSI in seven additional tumor types, including colorectal cancer, lung cancer, stomach cancer, and lymphadenoma." (PMID 36386816, 2022). "In conclusion, our study revealed the role of ANXA1, NNMT, Fibulin-5 and UQCRC1 in gastric cancer progression." (PMID 27941907, 2016).
colorectal cancer (23 papers, 2009 to 2025). A primary or metastatic malignant neoplasm that affects the colon or rectum. "Among the 520 patients with early-stage colorectal cancer, NNMT overexpression was significantly associated with both shorter overall and disease-free survival (p = 0.0056 and p = 0.0260, respectively)." (PMID 35177765, 2022). "The expression of NNMT was also found to be associated with the proliferation of colorectal cancer and its sensitivity to 5-fluorouracil." (PMID 35884600, 2022). "A large number of subsequent studies demonstrated that NNMT is aberrantly expressed and associated with a poor prognosis in various cancers, such as colorectal cancer, gastric cancer, hepatocellular carcinoma, and lung cancer." (PMID 31101119, 2019). "NNMT is a crucial enzyme in metabolism of nicotinamide and xenobiotic drugs, hence its overexpression may aid in risk stratification of drug treatment of colorectal cancer." (PMID 35177765, 2022). "Nicotinamide N-methyltransferase (NNMT) has emerged as a central node linking metabolic reprogramming to epigenetic remodeling in colorectal cancer." (PMID 41020873, 2025). "NNMT mRNA expression is indeed very low in colorectal cancer cells, whereas, for example, kidney cancer or mesothelioma cells express much higher levels of NNMT." (PMID 35177765, 2022). "In summary, our study examined several cohorts of colorectal cancer patients and identified tumor stromal NNMT overexpression as a potential prognostic marker indicating poor clinical outcomes in early-stage colorectal cancer." (PMID 35177765, 2022). "Based on the currently available TCGA and CPTAC datasets for which both gene and protein sequencing data are available, NNMT protein abundance is positively correlated with abundance of its mRNA transcript in colorectal cancer." (PMID 35177765, 2022). "In contrast, colorectal cancers show NNMT protein expression in tumor stroma that varies between individual patients, ranging from few positive tumor stromal cells to strong expression in most stromal cells." (PMID 35177765, 2022). "In an attempt to understand NNMT interaction network in colorectal cancer, we examined related genes and proteins in the TCGA colorectal cancer cohort." (PMID 35177765, 2022). "The inhibition of NNMT expression in colorectal cancer HT-29 cells diminishes 5-FU resistance, while upregulation of NNMT in SW480 cells enhances it." (PMID 33446144, 2021). "Nicotinamide N-methyltransferase (NNMT) plays multiple roles in improving the aggressiveness of colorectal cancer (CRC) and enhancing resistance to 5-Fluorouracil (5-FU), making it an attractive therapeutic target." (PMID 34572508, 2021). "An association between the elevated expression of NNMT and several cancers, including pancreatic and colorectal cancers, has been reported, and the potential of NNMT as a blood tumor marker for bladder and colorectal cancer has been suggested." (PMID 32992891, 2020). "NNMT is over-expressed in various tumors, including glioblastoma, pancreatic cancer, papillary thyroid cancer, renal carcinoma, colorectal cancer, oral squamous cell carcinoma, lung cancer, and bladder cancer." (PMID 27323852, 2016). "Indeed, overexpression of NNMT in SW480 colorectal cancer cells reduces NAD+ levels, whereas an NNMT downregulation in HT29 cells elevates cellular NAD+ content." (PMID 38396769, 2024). "Clinical correlation analyses of 572 patients with early-stage cancers reveal that NNMT protein overexpression is significantly associated with shorter overall and disease-free survival, but no such correlation is found in late-stage colorectal cancer." (PMID 35177765, 2022). "NNMT overexpression has been reported to decrease drug sensitivity and enhance chemoresistance in breast cancer, esophageal squamous cell carcinoma, and cell lines of colorectal cancer and melanoma." (PMID 35177765, 2022).
colorectal cancer (continued). "It will be interesting to explore in future studies whether NNMT overexpression can be used as a marker to guide adjuvant chemotherapy in colorectal cancer treatment." (PMID 35177765, 2022). "Previously, NNMT was identified as a novel serum marker colorectal cancer." (PMID 33446144, 2021). "Interestingly, an enhanced expression of NNMT has been reported in a number of cancers, such as glioblastoma, stomach adenocarcinoma, papillary thyroid cancers, renal, and oral squamous cell carcinomas, colorectal cancer, bladder, lung and pancreatic cancers." (PMID 23990942, 2013). "In a quest for prognostic biomarkers in early-stage colorectal cancer, we investigated NNMT (nicotinamide N-methyltransferase) in large cohorts of patients." (PMID 35177765, 2022). "Lastly, the function of NNMT and its product 1-methyl-nicotinamide (1-MNA) on migration and invasion in colorectal cancer cells was analyzed by wound healing assay and transwell assay." (PMID 34539890, 2021). "However, abnormal NNMT expression has been identified in several types of tumors, including glioblastoma, stomach adenocarcinoma, papillary thyroid cancers, colorectal cancer, hepatocellular carcinoma, lung cancer and renal cancer, suggesting that NNMT may have a significant role in cancer." (PMID 25120681, 2014). "We also have previously reported that NNMT overexpression inhibits the activation of ASK1-p38 pathway via MNA production, which results in a decrease in the apoptosis induced by 5-fluorouracil (5-FU) to enhance resistance in colorectal cancer cells." (PMID 31101119, 2019). "NNMT methylates NAM and is expressed at high levels in several cancers like renal clear cell carcinoma, bladder cancer, and the gastric and colorectal cancers." (PMID 31294922, 2019). "NNMT was identified as a novel serum marker for human colorectal cancers although this protein is not thought to be secreted." (PMID 19216803, 2009). "Since NNMT is a methyltransferase that uses the same methyl donor (SAM) as other methyltransferases, we asked whether its expression differed in CIMP-high and CIMP-low colorectal cancers." (PMID 35177765, 2022).
glioblastoma (20 papers, 2009 to 2026). The most malignant astrocytic tumor (WHO grade IV). "Conversely, NNMT, encoding for the enzyme responsible for the synthesis of N1-methylnicotinamide, was among the 79 transcripts up-regulated by dexamethasone in all four glioblastoma cell lines, and its expression pattern was confirmed at the protein level." (PMID 41576167, 2026). "Together, these results demonstrate that NNMT is a previously unrecognized transcriptional target of the GR in glioblastoma cells." (PMID 41576167, 2026). "In tumors of patients with glioblastoma, NNMT outcompetes NAMPT, the enzyme responsible for NAD+ production, for nicotinamide." (PMID 41576167, 2026). "This isotope distribution indicates that in human glioblastoma, the NNMT-dependent conversion of nicotinamide to N1-methylnicotinamide exceeds that of nicotinamide to NAD+." (PMID 41576167, 2026). "Here, a metabolomic screen in naïve glioblastoma cells treated with dexamethasone revealed the accumulation of N1-methylnicotinamide, a nicotinamide N-methyltransferase (NNMT) product, through glucocorticoid receptor activation." (PMID 41576167, 2026). "This is exemplified in glioblastoma, where the overexpression of nicotinamide N-methyltransferase (NNMT) depletes the methyl donor S-adenosylmethionine (SAM), thereby promoting tumor growth." (PMID 39982908, 2025). "Some parts of the established experimental design aimed to explore the direct effect of PPZ on PP2A methylation, in three types of U87 glioblastoma cells (WT, NNMT knockout, and NNMT overexpressing), are problematic." (PMID 34073600, 2021). "Nicotinamide N-methyltransferase (NNMT) was also reported to regulate mesenchymal glioblastoma stem cell maintenance by depletion of methionine and shift tumor towards a mesenchymal phenotype and accelerated tumor growth." (PMID 30626092, 2019). "Recently, it has been reported that NNMT silencing is able to activate PP2A via its effects on LCMT-1 in glioblastoma cells." (PMID 30192747, 2018). "On these bases, we hypothesized that the augmented activity of NNMT selectively found in glioblastoma tumors could be exploited for tumor metabolic imaging." (PMID 41576167, 2026). "Overall, these results demonstrate that expression and activity of NNMT are increased in glioblastoma tissue compared to normal brain and that conversion of blood-borne nicotinamide to N1-methylnicotinamide is selectively enhanced by dexamethasone in the tumor." (PMID 41576167, 2026). "Similarly, NNMT was shown to promote DNA hypomethylation in mesenchymal glioblastoma stems cells (GSCs) and to drive alterations in DNA methylation within the promoter regions of several genes in cancer-associated fibroblasts." (PMID 34068917, 2021). "Although the involvement of AOX1 activity has not been addressed directly, some insight may be gained from the study aimed to explore the role of high NNMT expression in glioblastoma." (PMID 34073600, 2021). "Nicotinamide N-methyltransferase (NNMT) is essential for histone methylation, and its expression results in dysregulated transcription and translation of several key genes involved in the development of glioblastoma." (PMID 30349486, 2018). "NNMT is involved in reorganizing the methylome in glioblastoma cells, as NNMT inhibition upregulates the availability of methyl groups that leucine carboxyl methyl transferase 1 uses to methylate protein phosphatase 2A, further inhibiting serine/threonine kinases." (PMID 30349486, 2018). "Leveraging the tumor-specific activity of NNMT, we developed a novel 11C-nicotinamide–based positron emission tomography (PET) approach to visualizing glioblastoma tumors." (PMID 41576167, 2026). "Mesenchymal glioblastoma stem cells were found to preferentially upregulate NAMPT and NMMT expression through the transcription factor C/EBPβ, which interacts with NAMPT and NNMT gene regulatory regions." (PMID 34068917, 2021).
glioblastoma (continued). "Nicotinamide N-methyltransferase (NNMT) is a cytosolic enzyme that is overexpressed in a variety of human malignancies including lung cancer, glioblastoma, and gastric, pancreatic, and colorectal cancers." (PMID 31652035, 2019). "Moreover, dexamethasone treatment decreased the levels of the NNMT substrate SAM, specifically in the tumor tissue, recapitulating the results obtained with glioblastoma cells in culture." (PMID 41576167, 2026). "NNMT protein levels are higher in tissues taken from glioblastoma patients compared with those from patients with nonmalignant brain tumors." (PMID 30349486, 2018). "NNMT was found to be upregulated in kidney renal clear cell carcinoma (KIRC), kidney renal papillary cell carcinoma (KIRP), pancreatic adenocarcinoma (PAAD), glioblastoma multiforme (GBM), sarcoma (SARC), and lymphoid neoplasm diffuse large B-cell lymphoma (DLBC)." (PMID 35338115, 2022).